NRG1 (neuregulin 1)
Diseases named in the same sentence as NRG1 in open-access papers (continued):
Sharing a sentence is not in itself a finding about the gene and the disease.
lung small cell carcinoma (2 papers, 2021 to 2023). "Primary immunodeficiency (NES = -1.57, P = 0.028), small cell lung cancer (NES = -1.45, P = 0.009), and phosphatidylinositol signaling system (NES = -1.4, P = 0.037) were enriched in the NRG1 low-expressed phenotype." (PMID 37061663, 2023).
lymph node metastasis (2 papers, 2017 to 2021). "A recent report supported this association, showing an association between a variant of NRG1 (rs2439302) and lymph node metastasis in PTC26." (PMID 28703219, 2017). "It revealed 3 significant prognosis-related variables: lymph node metastasis, BRAF mutations and NRG1 deletions, where the significance level for lymph node metastasis was much close to 0.05, and limited to the number of samples, we did not perform an in-depth analysis on it." (PMID 34044811, 2021). "Interestingly, three SNPs of NRG1 were associated with lymph node metastasis in the BRAFV600E positive samples." (PMID 28703219, 2017).
malaria (2 papers, 2014 to 2018). Malaria is a serious and sometimes fatal disease caused by a parasite that commonly infects a certain type of mosquito which feeds on humans. "Taken together, our results indicate that judicious augmentation of NRG-1 during anti-malaria therapy against CM may be an effective therapeutic approach to increase effectiveness of current anti-malaria therapy against CM." (PMID 29636063, 2018). "We tested the effects of NRG-1 on ECM-associated brain inflammation and mortality in P. berghei ANKA (PbA)-infected mice and compared to artemether (ARM) treatment; an antimalarial currently used in various combination therapies against malaria." (PMID 24433482, 2014).
mastitis (2 papers, 2020). Inflammation of breast tissue during lactation or postpartum due to an obstructed duct or infection. "Genome-wide DNA methylation analysis of peripheral blood lymphocytes identified 1,078 differentially methylated genes between cows with S. aureus-mastitis and healthy cows, as well as the potential of NRG1, MST1, and NAT9 genes to serve as biomarkers of S. aureus mastitis progression." (PMID 33193625, 2020). "The NRG1, MST1, and NAT9 genes are closely related with the progression of S. aureus subclinical mastitis and serve as epigenetic markers for improving mastitis resistance in dairy cows." (PMID 32000686, 2020).
medulloblastoma (2 papers, 2020 to 2025). A malignant, invasive embryonal neoplasm arising from the cerebellum. "Moreover, when analyzing all medulloblastoma subgroups, elevated ANKRD1 and NRG1 expression correlated with lower patient survival." (PMID 32316671, 2020). "Next, we moved our attention to genes already related to medulloblastoma based on the literature and validated some of them, such as POSTN, BOC, VCAM1, and TP63 among the downregulated genes and ANKRD1, THBS1, NRG1, PTHLH, and HBEGF among the upregulated ones in DAOY and D283Med cells." (PMID 32316671, 2020).
mood disorder (2 papers, 2021). A cognitive disorder a disturbance in which the person's mood is hypothesized to be the main underlying feature. "In this study, we have extended the concept of PV NRG1/ErbB4 signaling, cortical disinhibition and plasticity, which we and others have formulated in the visual cortex, to the mPFC, which is relevant for cognition and mood disorders." (PMID 33627623, 2021).
motor neuron disease (2 papers, 2016 to 2020). "However, the roles of NRG1 in maintenance of motor neuron health and activity, as well as the functional consequences of its alteration in motor neuron disease, are not fully understood." (PMID 26891847, 2016). "Loss of NRG1 puncta at C-boutons of motor neurons in both sporadic ALS patients and two distinct lines of SOD1-ALS mice prompted us to test whether NRG1 has a neuroprotective potential for motor neuron disease." (PMID 26891847, 2016). "Our study is the first to demonstrate dysregulation of the NRG1-ErbB4/3 axis in both human and mouse ALS and to provide support for NRG1 supplementation as a possible therapeutic option for motor neuron disease." (PMID 26891847, 2016).
renal cell carcinoma (2 papers, 2021 to 2023). "Here we present a case of a 49 year old man with an aggressive renal cell carcinoma bearing a novel pathogenic KAT6A::NRG1 fusion." (PMID 36816927, 2023).
sarcoidosis (2 papers, 2020 to 2021). Sarcoidosis is a multisystemic disorder of unknown cause characterized by the formation of immune granulomas in involved organs. "Interestingly, the level of neuregulin-1 (NRG1), a protein involved in cancer progression, was also upregulated in patients with sarcoidosis." (PMID 33915715, 2021). "The role of NRG-1 in sarcoidosis is not clarified, but it may be associated with cell survival and proliferation." (PMID 33915715, 2021). "In several pathological conditions, including sarcoidosis, the quantity of exosomes in BAL fluid is increased; they present a higher expression of MHC class-I and -II and other bioactive molecules, such as neuregulin-1 and they can activate autologous cells to produce inflammatory cytokines." (PMID 33238426, 2020).
steatosis (2 papers, 2022 to 2023). Increased lipid within the cytoplasm of cells. "On the other hand, in the presence of steatosis, the abolishment of NRG1 or PAK1 effects affected IGF1 since in steatotic livers from the BD+anti-NRG1+LT and BD+anti-PAK1+LT groups, IGF1 levels were lower than in the BD+LT group." (PMID 35625715, 2022). "We demonstrated that exogenous NRG1 may not be appropriate for application in the clinical practice of LT from DBDs, independently of the type of liver (the presence or absence of steatosis)." (PMID 35625715, 2022). "The inhibition of either NRG1 or PAK1 (BD+anti-NRG1+LT and BD+anti-PAK1+LT groups) decreased VEGFA in non-steatotic livers, while no changes were observed in the presence of steatosis when compared with the results obtained in the BD+LT group." (PMID 35625715, 2022).
Tremor (2 papers, 2016 to 2018). An unintentional, oscillating to-and-fro muscle movement about a joint axis. "Transgenic mice overexpressing NRG1, previously linked to hypermyelination in these mice, displayed tremor, impaired performance on rotarod and decreased prepulse inhibition performance." (PMID 27045844, 2016). "After 2, 4 and 7 weeks of antibody treatment, significant and dose-dependent increases in tremor-associated movement intensities, referred to as the “movement index”, were observed for the anti-NRG1 treatment groups in comparison with the control group (anti-Ragweed)." (PMID 29844389, 2018). "Our findings demonstrate that tremor is caused by anti-NRG1 treatment, possibly via induced stabilization of transmembrane NRG1, suggesting it may be linked to certain genetic drivers of the disorder." (PMID 29844389, 2018). "Once again, we found that anti-NRG1, but not anti-ErbB3/anti-ErbB4 combination treatment caused tremor and a decrease in rearings." (PMID 29844389, 2018). "In addition, it is also possible that the tremor present in the anti-NRG1 treated mice could affect both rearings and wire hang latency by impacting balance." (PMID 29844389, 2018). "However, we saw no tremor, or observable motor changes in anti-ErbB4 treated mice, indicating that the observed effects of anti-NRG1 likely did not depend on receptor mediated signaling." (PMID 29844389, 2018). "Moreover, treatment with a combination of both anti-ErbB3 and anti-ErbB4 inhibitory antibodies did not result in tremor or sensorimotor gating deficits, further supporting a receptor-independent mechanism of the anti-NRG1 phenotypes." (PMID 29844389, 2018).
type 2 diabetes (2 papers, 2015 to 2017). "We also tested the hypothesis that NRG1/ERBB abundance and signalling are disturbed in skeletal muscle of db/db mice and that chronic treatment with NRG1 improves mitochondrial function in this animal model of type 2 diabetes." (PMID 28496106, 2017). "We thus tested this hypothesis by evaluating the effects of chronic and acute NRG1 treatment on the systemic glucose metabolism regulation in db/db mice, an animal model of type 2 diabetes." (PMID 26230680, 2015). "We then demonstrate that chronic treatment with NRG1 also improves glucose clearance during GTT in db/db mice, suggesting that the NRG1 pathway may represent a promising therapeutic target for type 2 diabetes." (PMID 26230680, 2015).
uterine fibroids (2 papers, 2022). "SATB homeobox 2 and neuregulin 1 were proved to be the upregulated hypermethylated genes involved in the pathogenesis of uterine leiomyoma by activating the WNT/β-catenin and TGF-β pathways." (PMID 36386836, 2022). "To know whether mutations in MED12 are associated with the upregulation of upstream regulators, SATB2 and NRG1 in uterine fibroids, we examined the DNA methylation and expression levels of SATB2 and NRG1 in the uterine fibroids with and without MED12 mutations." (PMID 35618793, 2022).
vascular dementia (2 papers, 2020 to 2022). A degenerative vascular disorder affecting the brain. "In a study on vascular dementia, plasma NRG1 levels were found to be increased and inversely correlated to cognitive severity." (PMID 35606871, 2022).
Vestibular schwannoma (2 papers, 2021 to 2023). A vestibular schwannoma (also known as acoustic neuroma, acoustic neurinoma, or acoustic neurilemoma) is a benign, usually slow-growing tumor that develops from the VIIIth cranial nerve supplying the inner ear. "Quantitative analysis of the distribution of NRG1, pS6 and pNDRG in tissue sections from four different human vestibular schwannomas (VS) revealed that each exhibited striking intra- and intertumoral heterogeneity." (PMID 36944680, 2023). "In sporadic vestibular schwannomas, Erbb2-interacting protein (Erbin) gene was found to be up-regulated, while Erbin was able to participate in tumor production through neuregulin 1 (Nrg1) activation of pathways such as PI3K/AKT." (PMID 33673851, 2021).
acute coronary syndrome (1 paper, 2025). Signs and symptoms related to acute ischemia of the myocardium secondary to coronary artery disease. "A previous study revealed that patients with acute coronary syndrome (ACS) or T2DM patients wtih high CAD risk have lower levels of NRG-1 than healthy controls or hypertensive controls." (PMID 40747492, 2025).
acute respiratory distress syndrome (1 paper, 2019). Progressive and life-threatening pulmonary distress in the absence of an underlying pulmonary condition, usually following major trauma or surgery. "The same group has demonstrated elevation in BAL and plasma NRG1 in adults with acute respiratory distress syndrome, suggesting that NRG1 can act as a biomarker for lung injury, and implicating NRG1-mediated HER2 activation in diverse inflammatory lung pathologies." (PMID 30813222, 2019).
anemia (1 paper, 2021). A reduction in the number of red blood cells, the amount of hemoglobin, and/or the volume of packed red blood cells. "It is possible that children with SCA who have more severe anemia (and expected higher plasma free heme) may show associations between hematologic values and NRG-1." (PMID 35935682, 2021).
Arthritis (1 paper, 2021). Inflammation of a joint. "Among 35 MD-associated genes with drug-interaction data, four MD-specific genes interacted with drugs associated with arthritis: NR3C1 (N = 6), NRG1 (N = 2), CD40 (N = 2), TYR (N = 1)." (PMID 34603368, 2021).
atopic dermatitis (1 paper, 2025). "NRG1 can reduce levels of pro-inflammatory cytokines through NF-kB signaling and exhibits anti-inflammatory effects in cultured keratinocytes and in atopic dermatitis-like mice." (PMID 41153404, 2025).
Atrophy (1 paper, 2018). Any weakening or degeneration, especially through lack of use. "Thus, the modulation of the NRG1/ErbB system was analysed in this model of pharmacological-induced atrophy." (PMID 29568012, 2018).
Auditory hallucination (1 paper, 2025). Perception of sounds without auditory stimulus. "NRG1 is another gene associated with auditory hallucinations and persecutory delusions." (PMID 40943654, 2025).
benign thyroid tumors (1 paper, 2024). "The NRG1 gene encodes neuregulin 1, a signaling protein involved in the development of both malignant and benign thyroid tumors." (PMID 38571492, 2024).
bladder tumours (1 paper, 2011). "We measured NRG1 expression by real-time quantitative RT–PCR and ERBB receptors by western blotting and immunohistochemistry in bladder tumours and cell lines." (PMID 21364580, 2011).
bone sarcoma (1 paper, 2022). A sarcoma that arises from the bone. "NRG1 fusions were present in two patients in the STS cohort (dedifferentiated liposarcoma and synovial sarcoma) and one in the bone sarcoma cohort (osteoblastic osteosarcoma)." (PMID 36741731, 2022).
Bovine mastitis (1 paper, 2016). INFLAMMATION of the UDDER in cows. "Further functional analysis revealed that three genes, NRG1, MST1 and NAT9, were strongly correlated with the progression of S. aureus subclinical mastitis and could be used as powerful biomarkers for the improvement of bovine mastitis resistance." (PMID 27411928, 2016).
brain inflammation (1 paper, 2014). "This study suggests that NRG-1 attenuates ECM-associated brain inflammation and injuries and may represent a novel supportive therapy for the management of CM." (PMID 24433482, 2014).
ciliopathy (1 paper, 2021). A genetic disorder of the cellular cilia or the cilia anchoring structures, the basal bodies, or of ciliary function. "This indicates that pathogenic CRD-NRG1 signals affecting the ventricular system derive from cells other than glutamatergic neurons, eg, ependymal cells, possibly causing abnormal autocrine NRG1/ErbB4 signaling, ciliopathy, and altered cerebrospinal fluid circulation." (PMID 33871014, 2021).
Cirrhosis (1 paper, 2007). A chronic disorder of the liver in which liver tissue becomes scarred and is partially replaced by regenerative nodules and fibrotic tissue resulting in loss of liver function. "NRG1 was identified by microarray analysis to be decreased in cirrhosis, elevated in dysplasia, and again down-regulated during all four stages of HCC." (PMID 17640361, 2007).
clear cell carcinoma (1 paper, 2024). "All fusion-positive samples were diagnosed as borderline/low grade or high grade serous carcinoma, but one case harboring a RBPMS::NRG1 fusion was classified as clear cell carcinoma." (PMID 39575425, 2024).
cocaine use disorder (1 paper, 2023). A substance-related disorder that involves the recurring use of cocaine despite negative consequences. "While there are some clinical reports linking cannabis and alcohol use problems with NRG1 mutations, to date there have been no investigations into NRG1 mutations and association with cocaine use disorder." (PMID 37233814, 2023).
colitis (1 paper, 2024). Inflammation of the colon. "Our study identified a unique subpopulation of fibroblasts enriched during early colitis healing, characterized by the expression of neuregulin-1." (PMID 38674054, 2024). "By analyzing the public single-cell RNA-sequencing datasets and employing a dextran sulfate sodium (DSS)-induced colitis model, we investigated the cell source of Nrg1 expression and its potential regulator in the process of epithelial healing." (PMID 38674054, 2024). "Nrg1 is highly expressed in stem-like fibroblasts that appear early in the mouse colon after inducing colitis with DSS." (PMID 38674054, 2024). "The effect of intervening with these stem-like Nrg1+ fibroblasts to improve the prognosis of colitis patients is still far from being achieved." (PMID 38674054, 2024). "Future attempts might be important to assess the efficacy of both NRG1 enhancement and IL-1-IL-1R signaling blockade in the clinical management of colitis." (PMID 38674054, 2024). "However, the dynamics and accurate derivation of Nrg1 expression during colitis remain unclear." (PMID 38674054, 2024).
cortical dysplasia (1 paper, 2010). "In our model of cortical dysplasia, reelin restores the radial glial scaffold as well as glia-guided migration; NRG1, however, had a more limited effect since radial glia were realigned, but neuronal migration was not improved." (PMID 21060844, 2010).
Crohn disease (1 paper, 2024). A gastrointestinal disorder characterized by chronic inflammation involving all layers of the intestinal wall, noncaseating granulomas affecting the intestinal wall and regional lymph nodes, and transmural fibrosis. "To demonstrate whether NRG1 and IL-1R were also co-expressed on colonic fibroblasts in IBD patients, we first analyzed their expression levels in the whole inflamed colon tissues from patients with UC and Crohn’s disease (CD) (GSE117993)." (PMID 38674054, 2024).
Dyskinesia (1 paper, 2019). A movement disorder which consists of effects including diminished voluntary movements and the presence of involuntary movements. "We are the first to report an association of the neurodevelopmental NRG1 rs3735781 GA genotype with the prolonged time to dyskinesia development, which corresponds to the NRG1’s protective role against neuroinflammation and oxidative stress." (PMID 31156712, 2019). "We report the associations of DRD2 rs1799732, NRG1 rs3735781, CAT rs1001179, SOD2 rs4880, and SLC22A1 rs628031 with time to occurrence of dyskinesia under the univariate analysis." (PMID 31156712, 2019).
follicular adenoma (1 paper, 2020). "Similarly to PTCSC3, NRG1 was also earlier associated with follicular adenoma." (PMID 33551988, 2020).
hippocampal atrophy (1 paper, 2022). "In this respect, we asked whether NRG1 administration prevents hippocampal atrophy in rats that consume obesogenic diets." (PMID 35220393, 2022).
Hyperhidrosis (1 paper, 2025). Abnormal excessive perspiration (sweating) despite the lack of appropriate stimuli like hot and humid weather. "Western blot analysis revealed that treatment with Polydatin (50 mg/kg/day for 1 week) significantly reduced the protein expression of BDNF and NRG-1 in the sympathetic ganglia compared to untreated hyperhidrosis mice (p = 0.009 and p = 0.035, respectively)." (PMID 40880648, 2025). "Polydatin significantly reduced the expression of both BDNF and NRG-1 in sympathetic ganglia, suggesting that it may attenuate hyperhidrosis by dampening sympathetic overactivation." (PMID 40880648, 2025). "In conclusion, this study demonstrates that Polydatin alleviates hyperhidrosis symptoms in a mouse model by downregulating AQP5 and NKCC1 expression in sweat glands and reducing neurogenic factors such as BDNF and NRG-1 in sympathetic ganglia." (PMID 40880648, 2025).
hyperlipidemia (1 paper, 2015). "The finding that NRG1-induced AKT phosphorylation at Ser473 can be blunted by pre-treating cardiac myocytes with palmitate suggests that over-nutrition or hyperlipidemia could lead to NRG1 resistance." (PMID 26230680, 2015).
hypoplastic left heart syndrome (1 paper, 2025). Hypoplastic left heart syndrome (HLHS) refers to the abnormal development of the left-sided cardiac structures, resulting in obstruction to blood flow from the left ventricular outflow tract. "Specifically, NRG1 and its receptor ERBB4 have been shown to be associated with LVOT defects, including AS, coarctation of the aorta, and hypoplastic left heart syndrome." (PMID 40149647, 2025).
interstitial cystitis (1 paper, 2017). A rare chronic debilitating urogenital disease characterized by urinary frequency, urgency, and pelvic pain. "Multiple binding profiles and various G-coupled protein receptors modulate NRG1/ErbB signalling, and we reported previously that NRG1/ErbB signalling was associated with inflammatory states of the rat bladder, such as interstitial cystitis." (PMID 29221474, 2017).
intestinal motility disorders (1 paper, 2019). "Regulation of nAChR subunit β4 by NRG1 and decreased nAChR β4 in patients with DD provide evidence that a lack of NRG1 may affect the composition of enteric neurotransmitter receptor subunits thus contributing to the intestinal motility disorders previously reported in DD." (PMID 31920561, 2019).